ALB (albumin)
Diseases named in the same sentence as ALB in open-access papers (continued):
Sharing a sentence is not in itself a finding about the gene and the disease.
Paraproteinemia (2 papers, 2007 to 2023). An abnormal immunoglobulin or part of an Ig (light chain) in the circulation. "Serum protein profiles for women with paraproteinemia revealed similar albumin levels in all three groups." (PMID 17875216, 2007). "Initial reports suggested that a subset of ALS patients may display OCB as part of their pathophysiology; however, these patients were also reported to have substantial increase in CSF albumin content and/or paraproteinemia." (PMID 37213901, 2023).
peanut allergy (2 papers, 2015 to 2025). "When Ara h 6, another 2S albumin from peanut, became available for molecular diagnosis, it was found to be an equally important predictor for peanut allergy [54•, 55]." (PMID 26233429, 2015). "When correlating the sensitization profiles with the DBPCFC results, Ara h 2, the 2S albumin from peanut, was the best predictor for clinical peanut allergy." (PMID 26233429, 2015).
pelvic infection (2 papers, 2021 to 2026). "Postoperative pelvic infection was also excluded from the analysis due to collinearity with albumin level (p = 0.031)." (PMID 34794409, 2021). "However, collinearity with albumin level prevented this factor being entered into the multivariate analysis, so further research is needed to explore whether pelvic infection is related to lymphatic leakage." (PMID 34794409, 2021).
peripheral arterial occlusive disease (2 papers, 2015 to 2017). "We observed that age ≧65 years, peripheral arterial occlusive disease, cancer, and eGFR showed a positive impact on early death, while serum albumin was associated with reduced risk of early death." (PMID 25856435, 2015).
Peripheral edema (2 papers, 2023 to 2025). An abnormal accumulation of interstitial fluid in the soft tissues of the limbs. "This subgroup had the longest hospital stays, a higher prevalence of peripheral edema, and significantly lower albumin and cholesterol levels." (PMID 40894478, 2025). "The presence of dyspnea also predicted MLHFQ scores, maintaining its significance when adjusted for LAVI, LVEDVI, LVESVI, LVEF (Model 2), and peripheral edema, LVESVI, LVEF, exercise capacity, and serum albumin (Model 3)." (PMID 36961061, 2023).
peritoneal disease (2 papers, 2009 to 2025). "In a separate analysis adding to the model information on bone and peritoneal disease, which have been associated with worse survival, albumin‐based markers were still strongly correlated to OS (data not shown)." (PMID 38477040, 2025).
pharyngitis (2 papers, 2020 to 2022). Inflammation of the throat most often caused by viral and bacterial infections. "DC, CC, and BC analysis indicated that ALB (serum albumin), PPARγ (peroxisome proliferator-activated receptor gamma), MAPK3 (mitogen-activated protein kinase 3), EGF (epidermal growth factor), and PTGS2 (prostaglandin G/H synthase 2) are closely related to pharyngitis." (PMID 33101439, 2020).
pheochromocytoma (2 papers, 2022 to 2025). "We observed decreased concentration of serum albumin in patients with adrenal masses: incidentaloma (-16%, p=0.0168), pheochromocytoma (-16%, p=0.0206) and Cushing’s/Conn’s adenoma (-14%, p=0.0068) than the controls." (PMID 36246875, 2022). "However, a case series reported in China found that 3 out of 6 pregnant women with pheochromocytoma exhibited positive urinary albumin results." (PMID 40746609, 2025).
plasma cell leukemia (2 papers, 2023 to 2024). An aggressive plasma cell neoplasm characterized by the presence of neoplastic plasma cells in the peripheral blood. "Low albumin concentration was found in patients with MM and plasma cell leukemia." (PMID 36999311, 2023).
plasma cell neoplasm (2 papers, 2023). A clonal proliferation of immunoglobulin-secreting plasma cells. "We also noticed the albumin level differs between plasma cell neoplasm cases and noncases groups." (PMID 37908181, 2023). "This implies that albumin level may play an important role in the incidence and progression of plasma cell neoplasm, but its mechanism is not clear." (PMID 37836494, 2023).
pneumococcal meningitis (2 papers, 2017 to 2022). An acute purulent infection of the meninges and subarachnoid space caused by Streptococcus pneumoniae, most prevalent in children and adults over the age of 60. "Wistar rats, subjected to either pneumococcal meningitis or artificial CSF (sham control), received Evans blue-albumin (EBA) intracisternally." (PMID 36036510, 2022).
pneumoconiosis (2 papers, 2025 to 2026). An occupational lung disorder caused by inhalation of dust particles. "In univariable analyses, lower albumin and higher fibrinogen and FAR were associated with pneumoconiosis." (PMID 41696815, 2026). "Compared with non-pneumoconiosis participants, pneumoconiosis patients were older and had longer work duration, higher hemoglobin, fibrinogen, blood lead levels, and FAR, as well as lower platelet count, albumin, and glomerular filtration rate." (PMID 41696815, 2026).
POEMS syndrome (2 papers, 2016 to 2025). POEMS syndrome is a paraneoplastic syndrome characterized by polyradiculoneuropathy (P), organomegaly (O), endocrinopathy (E), clonal plasma cell disorder (M), and skin changes (S). "It was well-accepted that low serum albumin and reduced eGFR was poor prognostic risk factor for POEMS syndrome." (PMID 39968457, 2025). "We found that albumin level was reduced, and effective therapy increased the albumin level in patients with POEMS syndrome." (PMID 39968457, 2025). "Serum alanine aminotransferase, aspartate aminotransferase, total bilirubin, total protein, and albumin levels were down-regulated, while uric acid level was up-regulated in patients with POEMS syndrome." (PMID 39968457, 2025). "Moreover, serum λ-LC was negatively correlated with albumin and positively correlated with globulin in patients with POEMS syndrome." (PMID 39968457, 2025). "There were several abnormal routine laboratory indexes in newly diagnosed POEMS syndromes, including the up-regulation of platelet count, uric acid, and λ-LC level as well as the down-regulation of RBC count, hemoglobin, total protein, albumin, Ca2+, and thyroid hormone levels." (PMID 39968457, 2025). "Importantly, patients with POEMS syndrome had significant reduced levels of alanine aminotransferase (ALT), aspartate aminotransferase (AST), total bilirubin (T-BIL), total protein, and albumin compared with controls (all P < 0.05)." (PMID 39968457, 2025).
portopulmonary hypertension (2 papers, 2013 to 2023). "Liver function tests, albumin level, and international normalized ratio may be useful in screening for portopulmonary hypertension in appropriate clinical scenario." (PMID 24027641, 2013).
pregnancy toxemia (2 papers, 2025 to 2026). "In the present study, does affected by pregnancy toxemia exhibited a marked decrease in metabolic parameters, including total protein, albumin, and globulin." (PMID 41012815, 2025). "Conversely, low albumin levels are usually associated with pregnancy toxemia, as the lack of available energy jeopardizes the health of both the mother and the fetus, highlighting the need for proper nutritional management during pregnancy." (PMID 41524807, 2026).
primary immunodeficiency (2 papers, 2024). "Previous studies among patients with primary immunodeficiency diseases have shown that a low calculated globulin (CG) level, obtained by subtracting albumin from total protein level, is associated with infection risk." (PMID 39337087, 2024).
proctitis (2 papers, 2022 to 2025). An inflammatory process affecting the anus. "MLRS were adjusted for covariates including age-binary variable, sex, BMI-binary variable, disease duration-binary variable, current cigarette smoker, MCS category, Disease extent > proctitis, MCS, MES-binary variable, ALB, FC, CRP, and >1 advanced therapy class failure (biologic or small molecule)." (PMID 41208873, 2025).
protein (2 papers, 2024 to 2025). "However, recent studies have shown that serum albumin reflects inflammation rather than nutritional status or protein–energy malnutrition." (PMID 39125410, 2024).
Pseudoarthrosis (2 papers, 2023). A pathologic entity characterized by a developmental defect in a long bone leading to bending and pathologic fracture, with inability to form a normal bony callus with subsequent fibrous nonunion, leading to the pseudarthrosis (or "false joint"). "Finally, serum albumin concentration in conjunction with vitamin D deficiency may be related to post-fracture and postoperative complications, such as pseudoarthrosis and infections in orthopedic patients." (PMID 37738466, 2023). "Prospective study, developed with patients who suffered fractures due to fragility of the foot and ankle (n = 108); the type of fractured bone, fracture mechanisms and classification were studied and also pseudoarthrosis, treatment, surgical dehiscence, anthropometry, 25OHD and albumin." (PMID 37738466, 2023).
psoriatic arthritis (2 papers, 2016 to 2022). Joint inflammation associated with psoriasis. "However, the effect estimate of CRP on DBP, serum albumin, and psoriatic arthritis showed nominal association at p < 0.05." (PMID 27327646, 2016).
renal agenesis (2 papers, 2023 to 2025). Renal agenesis (RA) is a form of renal tract malformation characterized by the complete absence of development of one or both kidneys (unilateral RA or bilateral RA respectively), accompanied by absent ureter(s). "The renal agenesis group [4.1 (IQR 3.7–4.4) g/dl] also had significantly lower albumin levels compared to the atrophic kidney (p = 0.04), hypoplastic kidney (p < 0.001), and nephrectomy (p = 0.03) groups." (PMID 40342889, 2025). "In addition, there were differences in laboratory parameters: MCDK patients had lower albumin levels, while renal agenesis patients had higher neutrophil levels." (PMID 40342889, 2025). "Albumin levels were decreased in MCDK patients, whereas neutrophil levels were elevated in patients with renal agenesis." (PMID 40342889, 2025). "Furthermore, laboratory findings revealed decreased albumin levels in MCDK cases and increased neutrophil counts in renal agenesis cases." (PMID 40342889, 2025).
Renal artery stenosis (2 papers, 2004 to 2025). The presence of stenosis of the renal artery. "Multivariate logistic regression analysis showed that baseline creatinine and serum albumin levels and renal artery stenosis were independent risk factors." (PMID 40686716, 2025). "Multivariate logistic regression analysis showed that baseline creatinine (p < 0.001), serum albumin (p = 0.034), and renal artery stenosis (p = 0.015) were independent risk factors for CPO." (PMID 40686716, 2025).
retinoblastoma (2 papers, 2002 to 2024). A malignant tumor that originates in the nuclear layer of the retina. "Twenty-five primary retinoblastoma tumours were analysed by real-time quantitative polymerase chain reaction to determine the genomic copy number of the N-MYC gene (2p24) relative to the copy number for REL, B2M, ALB, AF10 and MLL." (PMID 12232763, 2002).
Senile plaques (2 papers, 2021 to 2023). Senile plaques are extracellular deposits of amyloid in the gray matter of the brain. "A previous study showed parenchymal extravasation of Texas red-labelled bovine serum albumin after systemic administration in Tg2576 mice even before forming senile plaques, while the BBB permeability was unchanged in APP/PS1 mice and 3xTg-AD mice." (PMID 37993886, 2023).
sensory impairments (2 papers, 2022 to 2025). "Multivariate logistic regression analysis was performed to adjust for confounding factors, including neurodegenerative diseases, sensory impairments, and serum albumin levels." (PMID 40598451, 2025).
sexual dysfunction (2 papers, 2017 to 2024). Disturbances in sexual desire and the psychophysiologic changes that characterize the sexual response cycle and cause marked distress and interpersonal difficulty. "Testosterone is an androgenic steroid hormone and binds to sex hormone-binding globulin and albumin, and low level of testosterone can result in sexual dysfunction." (PMID 28854246, 2017). "Various factors including estimated Glomerular Filtration Rate, Albumin-to-Creatinine Ratio, psychological aspects, medication use were found to be associated with sexual dysfunction in these CKD patients; Sexual dysfunction is prevalent in males with CKD and is, influenced by multiple factors." (PMID 38649741, 2024).
Skin rash (2 papers, 2013 to 2019). A red eruption of the skin. "High or normal serum albumin and the presence of skin rash associated with targeted chemotherapy treatment (EGFR tyrosine kinase inhibitors) were evaluated by two reviews; both were found to be associated with significantly better survival." (PMID 31311605, 2019).
spondyloarthritis (2 papers, 2018 to 2022). "In conclusion, traditional CVD risk factors, as represented by the ASCVD 10-year risk score, correlated with RDW and albumin in this spondyloarthritis cohort, and RDW was also associated with age, albumin, hemoglobin, race, HLAB27 status, CRP and statin treatment." (PMID 30363719, 2018). "In combination with larger nonautoimmune disease cohort data, these findings support further investigation of relationships between RDW, albumin, ALC, ASCVD 10-year risk score, and CVD risk in a larger cohort of spondyloarthritis patients." (PMID 30363719, 2018). "Albumin, hemoglobin, and ALC were also evaluated since these are biomarkers commonly followed in our patients with inflammatory disease, and HLA-B27 status was evaluated given its association with spondyloarthritis." (PMID 30363719, 2018).
Synthesis (2 papers, 2019 to 2021). "Further aspects of liver synthesis disorders are reduced albumin levels and alteration of the protein profile (i.e. a decrease in the albumin–globulin ratio)." (PMID 31218547, 2019).
Takayasu arteritis (2 papers, 2021 to 2024). A rare inflammatory large-vessel vasculitis primarily affecting the aorta and its major branches, but also other large vessels, causing stenosis, occlusion, or aneurysm. "C-reactive protein/albumin ratio and red blood cell distribution width can be used in the diagnosis of Takayasu arteritis, and C-reactive protein/albumin ratio, red blood cell distribution width, and monocyte/HDL ratio measurements can be used in the follow-up." (PMID 38775535, 2024).
temporal lobe epilepsy (2 papers, 2017 to 2024). A localization-related (focal) form of epilepsy characterized by recurrent seizures that arise from foci within the temporal lobe, most commonly from its mesial aspect. "Astrocytes can promote seizures and inflammatory responses in mice with temporal lobe epilepsy by activating the NF-κB signaling pathway, while ALB can reduce ROS by inhibiting the activation of NF-κB pathway." (PMID 40217387, 2024).
tetanus (2 papers, 2023 to 2024). A serious infectious disorder that follows wound contamination by the Gram-positive bacterium Clostridium tetani. "Almost all samples lacked immunoreactivity to human albumin and to a mock-purified 293 cell preparation; almost all samples were reactive to tetanus toxoid." (PMID 37219969, 2023).
Thiamine deficiency (2 papers, 2022 to 2023). Thiamine deficiency is a condition that occurs due to not enough thiamine (vitamin B1). "Experimental and clinical studies suggested that the disturbed metabolism of thiamine could lead to tissue-specific thiamine deficiency in the kidney and increase albumin excretion and microalbuminuria in peripheral nephropathy." (PMID 35265656, 2022).
thymic epithelial tumors (2 papers, 2021 to 2022). "In addition, a higher preoperative serum ALB level can often result in a more satisfactory prognosis, which is consistent with the findings of other studies reporting better prognosis in patients with thymic epithelial tumors with higher ALB levels." (PMID 34294070, 2021). "At the same time, many studies on hematological indicators have shown that Hb, NE, LY, platelet (PLT), NLR, ALB, GLB, ALB/GLB, platelet-lymphocyte ratio (PLR), NLR, and SII have potential to become prognostic hematological indicators for various tumors including thymic epithelial tumors." (PMID 34294070, 2021).
thyroid nodule (2 papers, 2010 to 2024). A small circumscribed mass in the THYROID GLAND that can be of neoplastic growth or non-neoplastic abnormality. "We compared three-dimensional (3D)-guided RFA using a matrix ultrasound transducer with conventional 2D-ultrasound guidance in an anthropomorphic thyroid nodule phantom incorporated additionally with temperature-sensitive albumin." (PMID 39400616, 2024).
Umbilical hernia (2 papers, 2025). Protrusion of abdominal contents through a defect in the abdominal wall musculature around the umbilicus. "Cirrhotic patients with umbilical hernia, particularly those over 65 years, with MELD scores greater than 15, low albumin levels, high white blood cell counts, and low platelet counts, are poor surgical candidates." (PMID 40731891, 2025).
uterine disease (2 papers, 2022 to 2026). "Previous studies have reported an association between decreases in protein markers, such as albumin and globulin, along with cholesterol, and postpartum uterine disease, suggesting a potential impact on reproductive function." (PMID 41514813, 2026).
vascular tumor (2 papers, 2021 to 2022). "Univariate analysis revealed that TNM stage, differentiation, circumferential margin, vascular tumor thrombus, nerve invasion, chemotherapy, radiotherapy, albumin, neutrophils, lymphocytes, and LANR all showed significant association with PFS (all P < 0.05)." (PMID 34150609, 2021).
venereal disease (2 papers, 2023 to 2025). "Cerebrospinal fluid analysis was normal for most patients with regard to pleocytosis, albumin glucose, chloride level, and antibodies against CMV, Toxoplasma, EBV, rubella, HSV and venereal disease research laboratory were negative." (PMID 37082207, 2023).
vitamin B1 deficiency (2 papers, 2021 to 2023). "Although a significant age difference was observed between the vitamin B1-deficient and non-deficient groups, other variables, such as albumin level, FIM, CCI, and medication count, did not significantly correlate with vitamin B1 deficiency." (PMID 38021762, 2023).
yang deficiency (2 papers, 2019 to 2022). Yang deficiency is a concept from traditional Chinese medicine. "Univariate logistic regression analysis showed that being female, older age, endocapillary hypercellularity, cellular/fibrocellular crescents, higher levels of HDL-C and URBC, and a lower level of ALB, SUA, and Hb were statistically significantly associated with Yang-deficiency (P < 0.05)." (PMID 35942383, 2022). "This study found that the serum albumin level was lower in the Yang-deficiency BC group than the non-Yang-deficiency BC group; this difference was also found in patients with and without blood-stasis BC." (PMID 31341498, 2019). "The serum albumin level was lower in the Yang-deficiency BC group than the non-Yang-deficiency BC group (P=0.009)." (PMID 31341498, 2019).
acute fatty liver of pregnancy (1 paper, 2025). "Currently, whether a decreased albumin can indicate a poor prognosis for women with acute fatty liver of pregnancy (AFLP) remains unknown." (PMID 40529137, 2025).
acute monocytic leukemia (1 paper, 2024). Acute monoblastic leukemia (AML-M5), is one of the most common subtypes of acute myeloid leukemia (AML) that is either comprised of more than 80% of monoblasts (AML-M5a) or 30-80% monoblasts with (pro)monocytic differentiation (AML-M5b). "In this study, we expose cells of the innate immune system and a human acute monocytic leukemia cell line (THP-1) to low doses of small-sized GO nanosheets functionalized with bovine serum albumin (BSA) and fluorescein isothiocyanate (FITC), to study their acute response after internalization." (PMID 38397858, 2024). "The present study focused on the biocompatibility of GO functionalized with bovine serum albumin (BSA) and fluorescein isothiocyanate (FITC) in healthy human leukocytes and in a human acute monocytic leukemia cell line (THP-1)." (PMID 38397858, 2024).